INS (insulin)
Diseases named in the same sentence as INS in open-access papers (continued):
Sharing a sentence is not in itself a finding about the gene and the disease.
Impaired glucose tolerance (continued). "Previous studies have demonstrated low levels of LPC in serum of individuals with impaired glucose tolerance and in subjects with insulin resistant and non-alcoholic fatty liver." (PMID 34722616, 2021). "The inappropriate response to HFD in control mice led to significantly higher body weight, impaired glucose tolerance and insulin sensitivity only in female Adcy5–/– mice." (PMID 33919448, 2021). "The results revealed that ZBPYR exhibited promising antidiabetic effects by moderating the increased RBG levels during the 3rd to 6th weeks of treatment and significantly improving the impaired glucose tolerance and insulin sensitivity." (PMID 33603781, 2021). "Serum levels of GAL, glucose and insulin have been measured in patients suffering from impaired glucose tolerance and in control subjects with normal glucose tolerance." (PMID 33802616, 2021). "In this study, we demonstrated that LNT dose‐dependently alleviated diabetic symptoms of chronic ethanol consumption model mice, manifested as increased random blood glucose, impaired glucose tolerance and insulin secretion." (PMID 33837638, 2021). "The progression of the disease is clinically manifested by increasing weight gain, impaired glucose tolerance, and high plasma insulin, triglycerides, and fasting glucose." (PMID 34803926, 2021). "The other patient developed only mild impaired glucose tolerance in spite of extremely elevated plasma insulin concentrations." (PMID 33555509, 2021). "This shows that I. batatas has the ability to inhibit insulin resistivity, poor insulin sensitivity, and impaired glucose tolerance which is a complication of a high level of Ca2+ in serum." (PMID 34639164, 2021). "In a preclinical model of low protein exposure throughout pregnancy (LP0.5), both male and female offspring exhibited impaired glucose tolerance and enhanced insulin sensitivity at six weeks of age." (PMID 34828683, 2021). "After 20 weeks, HFD mice also displayed elevated fasting blood glucose, and impaired glucose tolerance and insulin sensitivity." (PMID 34122403, 2021). "There was only a minor impaired glucose tolerance after long-term (16 weeks) in BCAA diet but insulin secretion and β-cell mass were normal." (PMID 33483593, 2021). "In line with our previous findings, the recipients injected with obese ATM EVs exhibited impaired glucose tolerance and insulin sensitivity." (PMID 34572101, 2021). "One-two hours after food intake, the levels of GAL, glucose and insulin were higher in the former group than in controls and, in addition, body weight was higher in patients with impaired glucose tolerance." (PMID 33802616, 2021). "OGTT and ITT showed that ZDF groups had symptoms of impaired glucose tolerance and decreased insulin sensitivity after 4 and 10 weeks of the experiment (p < 0.0001)." (PMID 34485269, 2021). "One human study supports this: a subgroup of participants with impaired glucose tolerance displayed normal 2-h glucose and reduced 2-h insulin following supplementation." (PMID 34333586, 2021). "Insulin sensitizing treatment with metformin plus pioglitazone for 3 months also improves arginine bioavailability in obese subjects with impaired glucose tolerance." (PMID 33079935, 2020). "CREB3L4, which regulates adipogenesis, has for instance been recently shown to have a critical role in metabolic phenotypes (weight gain, impaired glucose tolerance and decreased insulin sensitivity)." (PMID 32134384, 2020). "PNA mice present a mild metabolic phenotype, including increased fasting glucose level and impaired glucose tolerance but normal insulin sensitivity, and an early form of islet dysfunction in the pancreas." (PMID 32310267, 2020). "TRIF−/− mice showed impaired glucose tolerance in glucose tolerance tests, but their insulin tolerance tests were similar to those in TRIF+/+ mice." (PMID 33376487, 2020).
Impaired glucose tolerance (continued). "T2D is not only characterized by insulin insensitivity of the peripheral tissue but also by inadequate insulin secretion upon glucose treatment which finally results in an impaired glucose tolerance." (PMID 32082084, 2020). "The WM group exhibited impaired glucose tolerance, higher fasting and post-glucose insulin, and GLP-1 concentrations during the OGTT than the MS and CON groups." (PMID 32483245, 2020). "In our study, the HFD/STZ-induced diabetic mice exhibited high blood glucose concentrations and low plasma insulin levels with impaired glucose tolerance and insulin sensitivity, which are in concert with previous studies." (PMID 33043040, 2020). "Gao reported that dietary TMAO supplementation increased fasting insulin levels and exacerbated the impaired glucose tolerance in mice." (PMID 32859154, 2020). "When fed with chow diet, NR4A1 knockout mice showed improved insulin sensitivity, whereas, when fed with a high-fat diet, they showed impaired glucose tolerance and elevated circulating insulin levels." (PMID 33328994, 2020). "In a previous study, our research group demonstrated that ihs mice showed marked impaired glucose tolerance due to impaired insulin secretion." (PMID 32502168, 2020). "Female B6-ihs mice also showed impaired glucose tolerance and lower plasma insulin concentration than B6 mice during OGTT." (PMID 32502168, 2020). "Mitochondrial oxidative capacity does not show a day-night rhythm in older, overweight participants with impaired glucose tolerance and insulin sensitivity." (PMID 32659272, 2020). "INSC93S transgenic pigs showed impaired glucose tolerance due to reduced insulin secretion and mild fasting hyperglycemia." (PMID 33029223, 2020). "It is feasible that impaired insulin secretion contributed to impaired glucose tolerance: plasma insulin was raised in the knockout mice after administration of glucose, but perhaps if it had been even higher glucose tolerance would have been normal." (PMID 32904155, 2020). "The P2X7 KO mice show lower β-cell mass, impaired glucose tolerance, and defective insulin and interleukin secretion." (PMID 32984382, 2020). "In summary, the A0BΔpanc mice model is a more efficient and stable model for DM research, and is characterized by impaired glucose tolerance, abnormal islet structure, and decreased insulin positive cell number." (PMID 32764399, 2020). "Within 8 weeks of feeding, 145E mice showed increases in food intake, body weight, feeding efficiency, liver mass, epididymal fat mass, fasting glucose, and insulin, as well as impaired glucose tolerance." (PMID 32585823, 2020). "We observed that CAV1 KO mice were resistant to weight gain when on HFD, although they had high serum cholesterol and FFA levels, impaired glucose tolerance and were insulin resistant." (PMID 32718046, 2020). "Prolonged fasting duration (72 h or more) leads to greatly elevated postprandial glucose and insulin responses to the next meal, along with impaired glucose tolerance and insulin-mediated glucose disposal." (PMID 32707917, 2020). "Oxidative stress, which is an imbalance between formation and removal of highly reactive molecules, can lead to impaired insulin sensitivity, β-cells' dysfunction, impaired glucose tolerance, and eventually T2DM." (PMID 32655759, 2020). "The effect of NMN in reversing impaired glucose tolerance was milder in males compared to females, and insulin tolerance remained unchanged in male mice." (PMID 32411700, 2020). "The fasting glycaemia and insulin levels were increased in F1-programmed females in adulthood, which suggests a possible inclination to impaired glucose tolerance." (PMID 32245222, 2020). "Poor sleep quality is related to impaired glucose tolerance and insulin sensitivity, and increased interleukin 6 level, and plasma concentration, which increases the risk of stroke." (PMID 32457400, 2020).
Impaired glucose tolerance (continued). "Other observations included impaired glucose tolerance, abnormal insulin secretion, and β-cell dysfunction." (PMID 32398147, 2020). "Twelve male overweight volunteers with impaired glucose tolerance and insulin sensitivity stayed in a metabolic research unit for 2 days under free living conditions with regular meals." (PMID 32659272, 2020). "The neuroprotection caused by propranolol was accompanied by a reduction in fasting glucose, fasting insulin, glucose tolerance impairment, plasma CRP, plasma free fatty acids, plasma corticosterone, brain oxidative stress, and brain inflammation." (PMID 32492962, 2020). "Circulating IL-6 levels are increased in insulin-resistant states, such as impaired glucose tolerance and T2DM." (PMID 33043822, 2020). "Activators of both PPARα and PPARγ have been shown to improve insulin sensitivity and normalize impaired glucose tolerance in both humans and rodent models of IR." (PMID 32290353, 2020). "When compared with the control animals, HSuHF-treated rats displayed a metabolic phenotype compatible with obese prediabetes, displaying impaired glucose tolerance and insulin sensitivity, along with hypertriglyceridemia, and lipid peroxidation." (PMID 32218109, 2020). "Hypovitaminosis D seems to decrease the level of intracellular calcium, thereby reduce the level of insulin secretion and beta cellular dysfunction and, as a result, impaired glucose tolerance." (PMID 32874433, 2020). "These mice also displayed slightly impaired glucose tolerance, high fasting, and fed insulin levels, increased glucose mediated insulin secretion, reduced insulin sensitivity, decreased ambulatory activity, and increased fat to lean mass." (PMID 32849276, 2020). "This evidence is confirmed by the findings that miR-29a/b knockout mice have impaired insulin exocytosis and show alterations in peripheral tissue insulin sensitivity resulting in impaired glucose tolerance." (PMID 33375647, 2020). "Mice with deficient Grpr have impaired glucose tolerance and reduced glucagon-like peptide 1 (GLP-1) and early insulin responses to gastric glucose." (PMID 32527043, 2020). "NaSH administration at high doses increased serum glucose and impaired glucose tolerance and pyruvate tolerance, as well as decreased insulin secretion and serum insulin levels." (PMID 30621352, 2019). "Exposure to DOSS during development resulted in impaired glucose tolerance, insulin desensitization, increases in adiposity, and altered gene expression, circulating levels of adipokines, cytokines and phospholipids." (PMID 30728429, 2019). "Regarding glucose control, SUR1−/− rats showed impaired glucose tolerance, which indicated that there is little insulin release after the intraperitoneal injection of glucose into the SUR1−/− animals." (PMID 30616503, 2019). "Impaired glucose tolerance was mainly due to insulin resistance in muscles and fat tissues, as characterized by reduced insulin-induced muscle and fat absorption of glucose, resulting in reduced glucose utilization and increased postprandial blood sugar." (PMID 31215434, 2019). "The significantly increased FBG, RBG and HOMA‐IR as well as impaired glucose tolerance and insulin tolerance confirmed a stable diabetic and insulin‐resistant state of KKAy mice compared with C57BL/6J mice." (PMID 30945455, 2019). "Elevated fasting glucose and impaired glucose tolerance were accompanied by elevations in circulating insulin levels in fasting HFD-Obese mice." (PMID 30867005, 2019). "Due to the tissue-specific expression of this transporter, ZnT8-null mice display compromised β-cell function, reduced insulin secretion and low circulating insulin levels and impaired glucose tolerance." (PMID 30781350, 2019). "Animal studies have reported that total gastrectomy resulted in impaired glucose tolerance, possibly due to delayed insulin and increased glucagon release." (PMID 31292518, 2019).
Impaired glucose tolerance (continued). "As expected, long-term HF feeding resulted in impaired glucose tolerance, impaired insulin tolerance, and an elevated and diurnally invariant serum insulin profile." (PMID 29795456, 2019). "Mice fed a HF diet for 12 weeks manifested elevated FBG levels and serum HbA1C and impaired glucose tolerance and insulin sensitivity, which was consistent with previous studies." (PMID 31396097, 2019). "Whilst the evidence is inconclusive, palm oil is noted to have particular implications for nutrition and health, including increased risk for cardiovascular diseases, increased LDL cholesterol and impaired glucose tolerance (i.e., insulin sensitivity)." (PMID 31200513, 2019). "Hypothyroidism and SCH are related to insulin sensitivity and impaired glucose tolerance, and the ability of insulin to utilize glucose in muscle decreases." (PMID 31382952, 2019). "Mice treated with an HFHSD became overweight, had impaired glucose tolerance, were whole-body and β-cell insulin resistant after 4 wk of diet intervention." (PMID 29957055, 2019). "The resulting abdominal obesity plays a role in the progression of carbohydrate metabolism disorders, including impaired glucose tolerance, decreased insulin sensitivity, and T2DM, as well as increased cardiovascular risk." (PMID 30909620, 2019). "HFD/STZ diabetic rats in the present study showed an impaired glucose tolerance and insulin sensitivity as shown by the increased blood glucose, decreased insulin, and increased HOMA-IR value." (PMID 30915195, 2019). "The GK rats had impaired glucose tolerance, while administration of insulin lowered blood glucose during insulin tolerance test." (PMID 30940842, 2019). "Measures of glucose homeostasis are substantially altered in these mice as they have elevated blood glucose, insulin and C-peptide levels, impaired glucose tolerance, and reduced insulin sensitivity." (PMID 31939480, 2019). "In Experiment-2 we found an impaired glucose tolerance together with a lowered insulin response after acute and absolute fasting for 17 h in ad libitum fed animals." (PMID 31496992, 2019). "Fasting plasma glucose concentrations and fasting plasma insulin levels in diabetic mice were more than healthy group, which together show impaired glucose tolerance and insulin resistance." (PMID 31827624, 2019). "Impaired glucose tolerance and higher plasma insulin concentrations after intraperitoneal glucose injection in muscle-specific rac1 knockout (m-rac1-KO) mice actually demonstrate the physiological importance of Rac1 in insulin action in skeletal muscle." (PMID 30735546, 2019). "ERα knock-out mice exhibit increased visceral adiposity, impaired glucose tolerance and elevated insulin levels." (PMID 31882890, 2019). "During murine pregnancy, pharmacological blockade of GPR54 resulted in impaired glucose tolerance as a consequence of reduced glucose-induced insulin secretion." (PMID 31619585, 2019). "On the other hand, Cr potentiates the action of insulin in patients with impaired glucose tolerance, presumably by increasing insulin receptor-mediated signalling." (PMID 29164513, 2018). "In adulthood, exposed female offspring had higher blood glucose levels, impaired glucose tolerance, lower insulin secretion, and lower insulin levels than controls, while males had higher insulin levels." (PMID 30233498, 2018). "We previously demonstrated that the ability of Xen to amplify the effects of GIP on insulin and glucagon release is greatest in humans with impaired glucose tolerance and therefore, only subjects with impaired glucose tolerance were studied." (PMID 29466430, 2018). "In menopausal women who have impaired glucose tolerance, hormone replacement therapy can reduce blood glucose, increase insulin secretion and improve glucose tolerance." (PMID 30273360, 2018). "This resulted in impaired glucose tolerance and was accompanied by decreased insulin release, effects opposite to those observed with increased GK activity." (PMID 29748994, 2018).
Impaired glucose tolerance (continued). "Many studies showed that Cr(III) supplementation improved insulin sensitivity and blood glucose levels in animals and humans with impaired glucose tolerance, insulin resistance and diabetes." (PMID 29164513, 2018). "F2 male offspring of F1/C-GDM fathers exhibited impaired insulin sensitivity and increased body weight compared with control mice, and some F2 offspring developed impaired glucose tolerance at 8 weeks of age." (PMID 29801514, 2018). "DJ-1 also influences insulin secretion as well as β cell viability in the pancreas and DJ-1 knockout mice show increased ROS levels in islet cells, impaired glucose tolerance and decreased insulin secretion." (PMID 30072954, 2018). "Impaired glucose tolerance (IGT), which is associated with insulin insensitivity and is increasingly prevalent in the general population due to the increased incidence of obesity, also affects cognitive function." (PMID 29425182, 2018). "Developmental exposure to air pollutants caused beta cell dysfunction, reduced islet and beta cell size, lowered insulin secretion, and impaired glucose tolerance in adult male mice." (PMID 30233498, 2018). "Our data showed that impaired glucose tolerance and insulin sensitivity in the liver of HFD-fed mice were effectively improved by both a dose of SLT or OR." (PMID 30201876, 2018). "Animals fed HFD developed IRes, as evidenced by elevated fasting blood glucose concentration, impaired glucose tolerance, reduced insulin responsiveness and increased HOMA-IR index." (PMID 29739997, 2018). "Further, the loss of E-cadherin in mice seriously impacts on the ability of glucose to stimulate secretion of insulin from islets and results in impaired glucose tolerance in the face of normal insulin sensitivity." (PMID 29459424, 2018). "We found that TRIM31−/− mice had impaired glucose tolerance and decreased insulin sensitivity, accompanied by moderate inflammation activation." (PMID 29497383, 2018). "Two‐week administration of rotenone effectively lowered FBG, improved impaired glucose tolerance and insulin sensitivity of db/db mice." (PMID 29106036, 2018). "In conclusion, a 12-week exercise training program significantly improved the insulin sensitivity and insulin secretion in overweight or obese male adolescents even in those with impaired glucose tolerance." (PMID 29471797, 2018). "The inverse relationship between plasma kisspeptin levels and OGTT-derived indexes of glucose-stimulated insulin secretion was also maintained when subjects with normal glucose tolerance or impaired glucose tolerance (IGT) were analyzed separately." (PMID 28636637, 2017). "It is known that impaired glucose tolerance and reduced insulin sensitivity are present long before the onset of overt T2D." (PMID 28713332, 2017). "Downregulation of MEG3 expression in vitro corresponded with decreased insulin synthesis and secretion and increased β-cell apoptosis, consistent with in vivo findings of impaired glucose tolerance and reduced insulin secretion." (PMID 28829354, 2017). "Previous studies have suggested that a high-fat diet leads to impaired glucose tolerance and reduced insulin sensitivity." (PMID 29051579, 2017). "Our results confirmed impaired glucose tolerance in the nephrectomised cohort as revealed by their inability to restore basal blood glucose levels despite increased insulin levels." (PMID 28459862, 2017). "Hepatocyte Arnt deletion resulted in increased fasting glucose, impaired glucose tolerance, increased glucose production after pyruvate challenge, impaired insulin sensitivity and increased post-prandial serum TG." (PMID 29190746, 2017). "Here, our findings demonstrate that the exposure of LPD feeding during pregnancy and lactation resulted in low birth weight, impaired glucose tolerance, and lower insulin secretion in offspring, at as early as weaning age." (PMID 28264458, 2017).